CD151 (CD151 molecule (Raph blood group))
Diseases named in the same sentence as CD151 in open-access papers (continued):
Sharing a sentence is not in itself a finding about the gene and the disease.
tumor (continued). "Although TM4SF5, CD151, and CD63 can localize to the membrane surface and within the endosome system, their localizations could play critical roles in tumor progression and fibrotic phenotype development in the livers." (PMID 25033048, 2014). "Regardless of the Cd151 genotype, at least part of the largest tumor of each mouse had progressed to the carcinoma stage as determined by H&E staining." (PMID 25012362, 2014). "Future studies should aim to elucidate the mechanism by which PKCα regulates α3β1 function in tumor cells, and the interplay between CD9/CD81, CD151, and other TEM-resident proteins such as the major CD9/CD81 partners, IgSF proteins EWI-2 and EWI-F/CD9P-1, in regulating metastatic cell behaviors." (PMID 23613949, 2013). "This study suggests that, in patients with CD151 positive tumours, survival is significantly better than those with CD151 negative tumours." (PMID 21505452, 2011). "CD151 and TSPAN8 could also be identified as biomarkers for tumor cells in the primary tumor." (PMID 38255741, 2024). "However, in vivo studies in mouse cancer models suggest that TSPAN8 enhances cancer cell motility and migration mainly by recruiting integrins, whereas CD151 efficiently recruits and activates MMP9 and MMP13 to facilitate the degradation of the ECM and the invasion of tumor cells." (PMID 38275818, 2024). "Competing‐risks regression of time to death due to disease for high CD151, no epidermal growth factor receptor (EGFR) mutations group in early or advanced tumour, node, metastasis (TNM, American Joint Committee on Cancer [AJCC]) stage versus others in the Singaporean cohort." (PMID 38982031, 2024). "Interestingly, the integrin-absent pool of molecular aggregates of CD151, which presumably corresponds to the so-called integrin-free CD151 fraction, seems to have a regulatory role in cell-cell contact and tumor resistance to therapeutic agents." (PMID 33919420, 2021). "Based on these results, we demonstrated a new mechanism of CD151-mediated tumor progression by targeting EGFR/ErbB2 signaling pathway, by which CD151 promotes NSCLC proliferation, migration, and invasion, which may considered as a potential target of NSCLC treatment." (PMID 34108040, 2021). "Additionally, MET, TGFα, FGF2, CD151, and MMP3 are some of the oncogenic targets of miR-152 in human cancers; by targeting these genes, miR-152 leads to inhibition of cell proliferation and tumor metastasis." (PMID 33680048, 2020). "Therefore, we conjectured that CD151 could affect the expression of TGF-β1 and then attenuate the TGF-β1-induced MMPs expression, thus activate tumor metastasis." (PMID 29568359, 2018). "We detected endothelial CD151 at high levels on HCC tumor vessels and in vessels within the stroma surrounding the tumor, leading us to hypothesize that factors produced locally by the tumor may promote CD151 expression." (PMID 28473332, 2017). "On closer observation, it could be noted that the mice with high number of metastases in the Cd151+/+ group were also the mice with higher tumor burden suggesting that tumour burden rather than Cd151 status is the likely explanation." (PMID 25012362, 2014). "However, the difference between the median tumor latency of Cd151+/− versus Cd151+/+ mice was not significant (Log-rank test P = 0.7533)." (PMID 25012362, 2014). "However, there were minimal changes in cell motility or apoptosis of tumor cells upon CD151 removal (data not shown)." (PMID 25356755, 2014). "However, other clinical characteristics, including age, sex and tumor differentiation, were not significantly related to the expression of CD151." (PMID 23533596, 2013). "In addition, the disease-free survival rate of patients with CD151-positive tumours was significantly lower than that of patients with CD151-negative tumours (53.6 vs 61.2%, P=0.048)." (PMID 12838318, 2003).
tumor (continued). "Deciphering the role of exosomal CD151 and Tspan8 revealed that both tetraspanins contribute to matrix degradation that supports tumor and host cell motility, affect stroma and hematopoietic cells and are engaged in a feedback towards non-metastatic tumor cells, where they promote EMT." (PMID 25544774, 2015). "In addition, it was reported that CD151 may not affect tumour cell proliferation but could be involved in an early step in the formation of secondary metastatic lesions." (PMID 12838318, 2003). "Further, exosomes derived from CD151- and TSPAN8-competent tumor cells can be transferred into neighboring non-metastatic tumor cells, which induces expression of EMT-related genes." (PMID 38954230, 2024). "While there was minimal change in the expression of Twist, Snail or ZEB protein upon CD151 ablation (data not shown), expression of Slug proteins increased by 1.8-3.5-fold in OVCAR-5 and OVCAR-420 tumor cells." (PMID 25356755, 2014). "CD151 expression was analyzed by RT-PCR and immunoblotting in HGC tumor and matched nontumor tissues." (PMID 23533596, 2013). "In multivariate analyses, CD151 was significant for RFS and DSS (P=0.036 and 0.033, respectively) in triple negative (ER, PR and HER-2 negative) tumours (88/131)." (PMID 21505452, 2011). "Further, to confirm whether CD151 attributed its tumor promoting role to TGF-β1 in RCC or not, we stimulated the CD151-sh group cells with Rh TGF-β1 to restore the TGF-β1 expression." (PMID 29568359, 2018). "Indeed, anti-CD151 mAb (1A5) blocked metastases in SCID mice bearing Hep-3 tumors by inhibiting invasion and migration, although the antibody did not inhibit primary tumor growth." (PMID 29946318, 2018).
cancer (100 papers, 2003 to 2025). A tumor composed of atypical neoplastic, often pleomorphic cells that invade other tissues. "As a member of the TSPAN4 family, the critical role of CD151 in angiogenesis and cancer metastasis has been well established and is closely associated with various highly invasive cancers, such as lung cancer, colorectal cancer, and prostate cancer." (PMID 40830343, 2025). "The MBRG CD151 is a member of the tetraspanin family associated with the promotion of metastasis and plays a pro-metastatic role in various cancers." (PMID 39085893, 2024). "Among the 102 feature genes, eight genes (MYLK, GADD45A, ACADM, UQCR11, TST, PTCD3, SOD1, CD151) were significantly enriched in the cancer hallmark of adipogenesis." (PMID 36905391, 2023). "Previous studies had demonstrated that high CD151 gene expression was significantly associated with decreased OS in Japanese and Korean cancer patients." (PMID 34108040, 2021). "In the current review, we summarize recent advances in mechanistic understanding of the function and signaling of integrin-associated CD151 and other tetraspanins in multiple cancer types." (PMID 33919420, 2021). "CD151 was reported to be associated with cancer cell's aggressive cell proliferation and invasiveness in various malignancies such as lung, colon, breast, liver and prostate cancers, through interactions with laminin-binding α3β1, α6β1, and α6β4 integrins 3-5." (PMID 33767593, 2021). "The link between CD151 and human cancer was initially implicated following discovery of its co-translation with laminin-binding α3β1 integrin in human carcinoma cells or modulation of αIIbβ3 function in platelets." (PMID 33919420, 2021). "The increased apoptotic response was associated with reduced growth of CD151-ablated, drug-treated cancer cells." (PMID 30778617, 2019). "Both PKCα and another CD151-associated signaling molecule (PI4K) have been linked to cancer cell survival pathways." (PMID 30778617, 2019). "The results indicated that CD151 overexpression was significantly associated with cancer patients’ poor OS (pooled HR =1.498, 95% CI = 1.346-1.667, P<0.001)." (PMID 27888619, 2017). "In conclusion, the significant association between CD151 over-expression and cancer patients’ poor survival was clearly demonstrated in the present meta-analysis." (PMID 27888619, 2017). "We then used ceRDB database to predict the candidate ceRNAs of CD151 and chose 11 cancer-associated genes with higher scores to compare their expression levels between QGY- 7703 and HL-7702 cells." (PMID 27270320, 2016). "CD151 is the only tetraspanin whose role in cancer has been directly linked to altered TGFβ signaling." (PMID 25978409, 2015). "Because CD151 or its associated LB integrins have been shown to functionally collaborate with EGFR in other cancer types, these highly EGF-responsive cell lines were adopted for subsequent functional analyses." (PMID 26377974, 2015). "Of these substrates, CKAP4, CD9, and CD151 have been associated with initiation and progression of cancer." (PMID 24995331, 2014). "CD151 expression itself has been associated with poor patient outcome in several malignancies, including cancers of the breast, prostate, lung, and kidney, whereas it has also been found to correlate with improved survival in endometrial cancer." (PMID 25012362, 2014). "Evidence has demonstrated that CD151 forms complexes with integrins, c-Met, other tetraspanins, and itself, and is implicated in pathological processes associated with cancer progression." (PMID 21961047, 2011). "Investigating CD151 integrin association in different cancer types could improve prognostic power for survival analysis." (PMID 40464949, 2025). "Finally, we discuss the implications of the highly plastic nature and epigenetic susceptibility of CD151 expression, function, and signaling for clinical diagnosis and therapeutic intervention for human cancer." (PMID 33919420, 2021).
cancer (continued). "CD151 was the first tetraspanin associated with cancer development and progression." (PMID 33015133, 2020). "The conventional PKC isoforms (e.g., PKCα) can associate with CD151, may be needed for NIA-CD151 regulation of cell migration, and can play a role in cancer drug resistance." (PMID 30778617, 2019). "Also, CD151-associated α3 and α6 integrins are shown to enhance the aggressive behaviors of cancer stem cells." (PMID 26377974, 2015). "In addition, CD151 is frequently overexpressed on cancer cells and is functionally linked to cancer metastasis." (PMID 24553111, 2014). "More importantly, several cell adhesion proteins, such as BSG, ITGA2, CD9, SLC3A2 or CD151, were significantly enriched in TuNEPs and shared across cancer types." (PMID 40751052, 2025). "Different mechanisms have been described for how CD151 elicits its functions in driving cancer and metastasis." (PMID 40464949, 2025). "CD151 dysregulation is observed in various cancer types and is essential for cancer progression and metastasis." (PMID 39641053, 2024). "Herein, a MagLev-based biosensor platformfor exosome detectionwas proposed, and the platform was tested with solubilized ExoMPs,EpCAM as a cancer biomarker, CD151 as an NSCLC biomarker, and CD81as an exosomal biomarker." (PMID 38520356, 2024). "Therapeutic monoclonal antibodies (mAbs) targeting different tetraspanin members including TSPAN8, CD9, CD37 and CD151 have been explored in preclinical models and clinical trials for the treatment of hematological malignancies and carcinomas." (PMID 38275818, 2024). "CD151 is mostly expressed in endothelial cells and platelets, and is overexpressed in malignant tumors (prostate cancer, colorectal cancer, endometrial cancer, and non-small cell lung cancer)." (PMID 36613908, 2022). "This shows that the tetra-transmembrane superfamily protein CD151 promotes cancer migration and metastasis." (PMID 35747825, 2022). "To decipher how CD151 controls cancer sphingolipid metabolism, we analyzed the correlation between key cancer metabolic regulators in cancer cells." (PMID 36209197, 2022). "Extensive studies from our group and others have shown that CD151, the first member of the tetraspanin superfamily, contributes to the malignancy of human cancer." (PMID 36209197, 2022). "CD151, known as a member of the tetraspanin family, is actively involved in cancer progression via binding integrins and regulating growth factor receptors." (PMID 35685372, 2022). "We showed that CD151 silencing significantly regulated the expression of sphingolipid metabolism-related enzymes, which play key roles in the induction of cancer cell adhesion and metastasis." (PMID 36209197, 2022). "Collectively, these in vitro and in vivo investigations, along with clinical analyses, underpin CD151 as a premier player in human cancer metastasis." (PMID 33919420, 2021). "In cancer, a high level of CD151 is correlated with a grim prognosis for patients, and with elevated recurrence rates." (PMID 34830819, 2021). "Tetraspanins CD151, a transmembrane 4 superfamily protein, has been identified participating in the initiation of a variety of cancers." (PMID 34108040, 2021). "The pro-cancer effects of CD151 was mediated through interactions with integrins (α3β1, α6β1) growth factor receptors, and matrix metalloproteinase (MMP-2)." (PMID 34094979, 2021). "Despite the large diversity among tetraspanins, some have been clearly demonstrated to play key roles in cancer, among which CD151 and CD9 represent the most important ones." (PMID 34830819, 2021). "This notion is also supported by the evidence that altered CD151 promotes cancer cell resistance to targeted (anti-ErbB receptors) and chemo- therapies in multiple cancer types." (PMID 33919420, 2021). "Recent studies have shown that CD151 expression was increased in breast, prostate, lung, colon, skin, and other cancers, and elevated CD151 expression was correlated with advanced stage and poor prognosis." (PMID 34108040, 2021).
cancer (continued). "In the current review, we will summarize this dilemma for tetraspanin molecules, particularly CD151, and discuss their implications for conceptualizing the role of tetraspanins in human cancer at the cellular, signaling, and epigenetic levels." (PMID 33919420, 2021). "These diverse functions highlight a key basis for the crucial role of CD151 across a wide spectrum of human cancer." (PMID 33919420, 2021). "CD9 (Tspan29), CD63 (Tspan30) and CD82 (Tspan27) inhibit metastasis of various cancers, whereas Tspan8 and CD151 (Tspan24) promote metastasis." (PMID 33955149, 2021). "The role of tetraspanin CD151 in the development of cancer metastasis has been well documented so far." (PMID 34830819, 2021). "In some cancer types, the pro-metastatic role of CD151 appears to be achieved through strong synergy with other tetraspanins (e.g., TSPAN8)." (PMID 33919420, 2021). "It has long been advocated that CD151 is a crucial contributor of cell-cell adhesion in immortalized epithelial or carcinoma cells." (PMID 33919420, 2021). "CD151 is a member of tetraspanins scaffolding protein family that is involved in cell–cell adhesion, integrin interaction, cell signaling, cancer progression and metastasis." (PMID 32616845, 2020). "The expression and behaviour of α6β4 as well as its interaction with CD151 is described in hemidesmosome and cancer cells where CD151 plays a role in integrin trafficking and subcellular distribution." (PMID 32152440, 2020). "The potential of CD151 expression detection in exosomes as a screening tool has been explored where a high level of accuracy (72%) in detecting cancer in adenocarcinoma patients was observed." (PMID 32117989, 2020). "To date, there are only two studies that report that the expression of CD151 mRNA and protein abundance are modulated by therapies – anti-epileptic drugs and anti-cancer drugs, respectively." (PMID 32117989, 2020). "CD151 has previously been considered as a cancer target, due to its contributions to multiple stages of carcinogenesis." (PMID 30778617, 2019). "A panel of anti-cancer drugs similarly yielded increased apoptosis (i.e., cleaved caspase-3) in CD151 knockdown cells compared to control shRNA cells." (PMID 30778617, 2019). "CD151 is involved in cancer progression and neovascularization, and its overexpression is upregulated by NFE2L1 and influenced by DNA methylation to cause a high migration ability of cancer cells in early-stage PTC." (PMID 31126066, 2019). "CD151 expression is increased in breast, prostate, lung, colon, skin, and other cancers, and elevated CD151 expression correlates with advanced stage and poor prognosis in many of these human cancers." (PMID 30778617, 2019). "An increase in CD151 was similarly observed in A431 cells in response to a panel of additional anti-cancer drugs." (PMID 30778617, 2019). "A growing body of evidence have showed that changed expression of CD151 is related with cancer progression, invasion and metastasis." (PMID 29568359, 2018). "Among the human tetraspanins, Tspan8 and 12, CD9, CD37, CD63, CD81, CD82, and CD151 play a role in cancer progression." (PMID 29946318, 2018). "By contrast, CD151 is expressed in different types of cancer and high expression correlates with poor prognosis." (PMID 29946318, 2018). "Collectively, the function of CD151 is dependent on the specific microenvironment of different carcinoma." (PMID 29568359, 2018). "Altered expression of CD151 was involved in cancer growth, progression, motility, invasion, and metastasis." (PMID 27888619, 2017). "CD151 is a cell membrane molecular related to adhesion, which is important for cancer cell motility." (PMID 27556355, 2016). "In the current study, although using immunocytochemistry alone, we found strong expression of CD151, both in fibroblasts and cancer cells." (PMID 25885552, 2015).